VIM (vimentin)
Diseases named in the same sentence as VIM in open-access papers (continued):
Sharing a sentence is not in itself a finding about the gene and the disease.
tumor (continued). "Matrix metalloproteinase 9 (MMP9) and Vimentin play a crucial role in mediating migration and invasion processes, resulting in accelerated tumor metastasis." (PMID 32626749, 2020). "Western blot analysis of tumour spheres further showed that the expression of EMT‐associated proteins including N‐cadherin, vimentin, MMP‐9 and MMP‐1 was up‐regulated, whereas E‐cadherin expression was down‐regulated." (PMID 32396269, 2020). "CAFs were identified by the use of human-specific anti-VIMENTIN antibodies with parallel staining with pan-Vimentin antibodies detecting these cells and also mouse fibroblasts further away from the tumor area." (PMID 33046701, 2020). "Comparing EGF-treated MDA-MB-468 and MDA-MB-231 cells transfected with Vim Si1 in vitro before injection, we observed a clear diminution of human tumor cell content in lungs after vimentin silencing, as quantified by RT-qPCR." (PMID 32152404, 2020). "As such, vimentin is abundantly expressed in many tumor types, where its expression correlates with their aggressiveness and poor clinical outcome." (PMID 31940801, 2020). "The expression of N-cadherin and vimentin in the tumor tissue in the control group were significantly higher than that in the TRIM33 overexpression group." (PMID 32908919, 2020). "Collectively, these results strongly suggested that the combination of NC13 or Vms with cisplatin inhibited the EMT in tumor cells, particularly through the downregulation of vimentin resulting in suppression of pulmonary metastasis in vivo." (PMID 33230126, 2020). "To confirm that human CAF-like cells have not been replaced by murine fibroblast, we performed immunohistochemistry staining of tumor sections using a human-specific vimentin antibody." (PMID 32178458, 2020). "High expression of N-cadherin and Vimentin, and low expression of E-cadherin are considered as tumor markers to identify the EMT process." (PMID 32231566, 2020). "Meanwhile, miR-1298-3p agonist markedly decreased the protein levels of NID1 and vimentin, but increased the protein level of E-cadherin in tumor tissues, compared with NC group." (PMID 32355035, 2020). "Immunohistochemistry (IHC) was employed to examine the expression of E-cadherin and vimentin in a subset of representative parent and holoclone-derived (n = 3) tumour sections." (PMID 32647229, 2020). "E-cadherin, vimentin, and osteopontin (OPN) are proteins associated with tumor microenvironment (TME) remodelling that play key roles in cancer." (PMID 32731632, 2020). "Several epithelial markers were elevated in RE, Keratin 13, Keratin 20, and Gastrokine-1, relative to other groups, while neoplasia markers desmin and vimentin were elevated in BE and EAC compared to control." (PMID 32650561, 2020). "Immunohistochemistry (IHC) further revealed that tumor cells were Vimentin (+), α-Inhibin (+), CD99 (+), Calretinin (+), AE1/AE3 (+), EMA (−), PLAP (−), CD117 (−), and Ki-67 (+15%)." (PMID 32629665, 2020). "Densitometrical analysis revealed that while Au@Ag treatments did not influence the intratumoural protein levels of the fibroblast markers alphaSMA and Vimentin, these nanoparticles significantly reduced Osteopontin expression in the metastatic 4T1 tumours." (PMID 31964403, 2020). "We noted that in 153PT, an aggressive invasion front that was positive for Vimentin was observed and eventually, these aggressive tumor cells invaded into the liver, overgrowing and destroying hepatocytes." (PMID 32978388, 2020). "Among TME proteins, E-cadherin, vimentin, and osteopontin (OPN) have been recently reported as associated with tumor progression and patient outcome in various cancer models." (PMID 32731632, 2020). "The experimental results suggested that the high expression of MMP-9 in tumor cells promoted the occurrence of EMT by increasing the expression of Vimentin and reducing the expression of E-cadherin." (PMID 32698816, 2020).
tumor (continued). "Myofibroblastic tumor expresses CTGF in both endothelial cells and vimentin-positive tumor cells, particularly those around the blood vessels." (PMID 33195264, 2020). "A previous study suggested that platelets activate two signaling pathways in some tumor cells, leading to vimentin protein expression; one is the platelet-tumor contact-dependent activation of NF-κB signaling and the other TGF-β signaling." (PMID 32581653, 2020). "Western blot analysis presented that N-cadherin and Vimentin expression was diminished in tumor tissues from the sh-DLX6-AS1 group, while E-cadherin expression was strengthened." (PMID 32774164, 2020). "We found that the miR-146a-vimentin axis is involved in tumor formation, tumor stage and overall survival rate in ESCC patients." (PMID 33248456, 2020). "Our results showed that the expression of vimentin in SHI-1 tumour tissue was significantly inhibited after curcumin treatment (indicated by red arrows." (PMID 31854220, 2020). "Consistent with in vitro data, IHC staining showed weaker Vimentin and N-cadherin expression but stronger E-cadherin expression in tumor tissues from the P4HA2-silenced group than in those from the control group." (PMID 32226497, 2020). "It has already been demonstrated that TAMs play an important role in EMT by decreasing E-cadherin and increasing vimentin, thereby contributing to the invasiveness and metastatic properties of tumor cells." (PMID 32660099, 2020). "Ki67 expression often positively correlates with EMT-related factors such as survivin, vimentin and N-cadherin, thus promoting tumor aggressiveness." (PMID 33187205, 2020). "Further protein analysis of FGF18 overexpressed 786-O xenograft tumor compared to NC 786-O xenograft tumor also indicated elevated E-cadherin expression, decreased N-cadherin, Vimentin, and EMT related transcription factors." (PMID 33117668, 2020). "VIM is a marker of tumor epithelial-mesenchymal transition and HCC metastasis; and Ki-67 is a marker of proliferation." (PMID 33585243, 2020). "Studies indicated that VIM translocated to tumor cell surface was phosphorylation‐dependent process." (PMID 31981446, 2020). "Results showed that vimentin knockdown markedly blocked the effect of circPTK2 expression in colony formation and tumor cell burden." (PMID 31973707, 2020). "We examined E-cadherin, β-catenin, and vimentin expression using immunohistochemistry and compared these with tumor and patient characteristics and treatment outcome." (PMID 32794417, 2020). "Similar results were acquired in SW620 and LOVO cells (high-level circPTK2) that vimentin overexpression significantly increased colony formation and tumor cell burden, which downregulated by the knockdown of circPTK2." (PMID 31973707, 2020). "On immunohistochemical staining, the tumor was positive for vimentin and anaplastic lymphoma receptor tyrosine kinase (ALK) and showed a positive signal pattern on ALK fluorescence in situ hybridization (FISH) test." (PMID 31641928, 2020). "We demonstrated that knockdown of LSD1 inhibited EMT process evidenced by increased protein levels of E-cadherin and decreased mRNA and protein levels of N-cadherin, Vimentin and Twist in tumor cell lines in vitro and xenograft in vivo." (PMID 32850370, 2020). "MMP9, VEGF, and vimentin are involved in promoting tumor metastasis, while E-cadherin is involved in its suppression." (PMID 32667904, 2020). "They showed that tumor emboli in the lymphovasculature which co-expressed vimentin and E-cadherin gradually lost the expression of vimentin to predominantly express E-cadherin." (PMID 32899433, 2020). "Compared with before NAC, the expressions of CD44, N-cadherin, β-catenin, and Vimentin in tumor tissues were significantly downregulated after NAC, while the expressions of E-cadherin and CD24 had no statistically significant change after NAC." (PMID 33282946, 2020).
tumor (continued). "While vimentin overexpression in cancer correlates with a high invasion of tumor growth (Satelli and Li, 2011), our results showed that with more metastasis vimentin increases." (PMID 32665775, 2020). "Contrarily, increased levels of vimentin and N-cadherin prompted that tumor progression and metastasis was enhanced by an upregulated miR-624-5p level." (PMID 31829261, 2019). "In tumors with ≥25% vimentin-positive tumor cells, numerous tumor cells co-expressed vimentin and PD–L1." (PMID 31546725, 2019). "Subsequently, the protein expression level of N-cadherin, Vimentin, MMP-2 and MMP-9 associated with metastasis ability of tumor were detected to further determine the effect of different treatments." (PMID 31391034, 2019). "In an orthotopic GBM mouse model, SAFit2 showed an anti-tumor effect, as assessed by reductions in tumor volumes, caspase activation and attenuated expression levels of PD-L1 and the mesenchymal marker vimentin." (PMID 31583120, 2019). "Previous studies have reported that Vimentin is functionally regulated by PTMs, especially phosphorylation, eventually contributing to enhanced tumor growth and metastasis." (PMID 31862882, 2019). "This iHDAC-induced switch in tumor cell shape due to tunneling tube formation was followed by vimentin and connexin 43 gene expression downregulation, an increase in radio sensitization, and intracellular Ca2+ signaling disruption." (PMID 31531023, 2019). "To investigate in more detail the impact of SLC-0111 and sunitinib—alone and in combination—on the extent of liver metastases, we stained whole mount liver tissue slices by immunofluoresence for vimentin to detect human tumor cells." (PMID 31319613, 2019). "Consistent with in vitro data, IHC analysis showed significantly reduced levels of Vimentin in tumour tissues treated by CYT997." (PMID 30450674, 2019). "Immunostaining showed that vimentin was positive in both the tumor and tumor stroma in the OE-Gal-1 group, and E-cadherin was negative in the tumor tissues." (PMID 31772662, 2019). "ObR and CD44 increased in tumor line cells, and vimentin increased in non-tumor cells, after incubation with hRAT-CMs vs. hRAN-CMs and control-CMs." (PMID 31534630, 2019). "A decreased percentage of tumor cells expressing PD-L1 and vimentin, according to histological examinations, suggested that in treated mice the tumor had a reduced aggressiveness." (PMID 31583120, 2019). "IFs in tumor cells have higher vimentin in contrast to keratin in normal cells; the presence of vimentin is a marker of EMT in mammary tissues." (PMID 31781558, 2019). "Immunofluorescence of tumor sections for vimentin and pan-cytokeratin was congruent with the RNA-level data." (PMID 30841919, 2019). "Glial fibrillary acidic protein (GFAP), vimentin, Ki67, S100 protein, neurofilament immunoreactivity were detected in the tumor produced on the CAM and infiltration of macrophages (CD68) and T cells (CD3+, CD8+) was observed." (PMID 31083409, 2019). "Vimentin was also positive throughout the tumor tissue; specifically, strongly positive in the epithelial layers and moderately positive in mesenchymal tumor cells." (PMID 31420001, 2019). "The tumor formed was collected and thin sections were stained with H&E, trichrome and with anti-Vimentin antibody." (PMID 31083409, 2019). "The tumor cells are diffusively positive for vimentin and S-100, focally positive for glial fibrillary acidic protein, and generally negative for epithelial membrane antigen, synaptophysin, chromogranin A, and neurofilament." (PMID 31689841, 2019). "Next, we evaluated the expression of Vimentin, the predominant intermediate filament of mesenchymal tumor cells, previously found up-regulated in CXCL12-stimulated GBM cells." (PMID 30082913, 2019).
tumor (continued). "From IHC results, Vimentin expression in 68/109 (62.4%) of patients was higher in the tumor samples than their adjacent normal controls." (PMID 31420013, 2019). "Our results showed that NF1-knockdown tumor had higher percentage of vimentin and CD44-positive cells." (PMID 30967630, 2019). "Only vimentin juxta nuclear dot was considered for aggresomes-positivity (59/93) representing 63.4% of tumor samples." (PMID 31471537, 2019). "We identified positive vimentin staining in both the tumor stroma and GC cells (Vimentin +) in 42 cases, and E-cadherin was decreased in those samples." (PMID 31772662, 2019). "Ninety tumors (48%) were vimentin-positive including 30 tumors (11%) with ≥25% vimentin-positive tumor cells." (PMID 31546725, 2019). "After 96 h of direct co-culture, we noted that with the gradient concentration of MDSCs in the culture, the proportion of Vimentin positive tumor cells increased." (PMID 31552179, 2019). "Of note, Treg-co-cultured B16-BL6 derived tumor tissues showed nuclear translocation of β-catenin as well as rearrangement of vimentin into dense structures around the perinuclear region." (PMID 31690033, 2019). "In most of the vimentin-positive carcinomas, numerous tumor cells co-expressed vimentin and PD–L1, supporting a narrow relationship between EMT and PD–L1 confirmed in both proper and TCGA cohorts." (PMID 31546725, 2019). "Together with Vimentin and N-cadherin, E-cadherin was found, indicating that the tumor tissue is composed of a heterogeneous population of epithelial and mesenchymal cells." (PMID 31450740, 2019). "During thisprocess, tumor cells partially or completely lose theirepithelial characteristics (EpCAM and CK) and acquiremesenchymal phenotypes (vimentin), which increasetumor cell plasticity, so as to easily escape from the primarytumor into blood." (PMID 30930631, 2019). "(E) The protein level of N-cad, Snai1, β-catenin and Vimentin in ECs treated with Exo-3B or Exo-3B-KD from tumor cells." (PMID 31477130, 2019). "Epithelial–mesenchymal transition (EMT) is widely perceived as a phenotypic switch and allows the tumor to adopt a metastatic and invasive behavior with the down-regulation of E-cadherin and the up-regulation of N-cadherin, vimentin, and other EMT markers." (PMID 30833362, 2019). "We further examined E-cadherin, N-cadherin, Vimentin, and β-catenin expression in orthotopic tumor samples after insufficient RFA." (PMID 30820716, 2019). "Then, we examined the protein expression of the key EMT regulators E‐cadherin and vimentin, which are the key genes in tumour invasion and metastasis, in p62‐overexpression and p62‐knowdown cells." (PMID 30793399, 2019). "EMT is one of the classical pathways for metastasis of tumor cells, and deletion of E-cadherin and increase of Vimentin are the basic events for the formation of EMT." (PMID 30858757, 2019). "Histopathological analysis showed an almost completely necrotic tumor with a share of less than 10% viable pleomorphic tumor cells expressing vimentin and CD99 and focal positive desmin." (PMID 31426804, 2019). "We noted that α5 colocalized in the tumor stroma with α‐SMA and vimentin, whereas tumor epithelial cells stained less." (PMID 31600854, 2019). "Using co-IF, co-expression of CK8 and the mesenchymal cell marker vimentin in tumor cells was observed (Fig 4D1-4)." (PMID 30677079, 2019). "Further, we detected the expression of E-cadherin, Pcdha8 and vimentin genes in the xenograft tumor tissues by immunofluorescent staining." (PMID 30531834, 2019). "The ectopic overexpression of miR‐139‐5p/miR‐940/miR‐193a‐5p promoted the protein levels of E‐cadherin, while reducing N‐cadherin and Vimentin in the tumour tissues." (PMID 30710422, 2019).
tumor (continued). "Results showed baicalein abrogated the increase of N-cadherin (P<0.01) and vimentin (P<0.01) and the decrease of E-cadherin in tumor bearing lung tissue (P<0.01)." (PMID 30949224, 2019). "Cytokeratin markers AE1 and AE3, along with vimentin, are usually co-expressed and are the most sensitive markers for this tumor." (PMID 31852518, 2019). "In contrast, ALDH+ CSCs resided within the core of the tumor with high expression of E-cadherin but low expression of vimentin and ZEB1, exhibiting an epithelial phenotype." (PMID 31394796, 2019). "AKT inhibitor MK2206 reversed effects of lncRNA-HGBC on expression of N-cadherin and vimentin, suggesting the tumor promoting role of lncRNA-HGBC requires AKT activation." (PMID 31752906, 2019). "Immunofluorescence analysis of EpCAM and vimentin revealed that tumor cells constitute more than 50% of the total cell populations in all 8 gastric PDCs, making them suitable proxies for comprehensive pharmacological analysis." (PMID 31850215, 2019). "The EMT has been demonstrated to play a role in tumor progression activities through the use of EMT-associated markers, such as mesenchymal-specific markers (i.e., vimentin and N-cadherin) and epithelial-specific markers (i.e., E-cadherin)." (PMID 30965609, 2019). "Knockdown of DLX6-AS1 down-regulated vimentin and N-cadherin, but up-regulated E-cadherin in the tumor tissues." (PMID 31787849, 2019). "The molecular hallmarks of EMT are canonically the decrease in epithelial traits, including E-cadherin and the increase in mesenchymal features such as vimentin and N-cadherin, leading to facilitated motility, plasticity, and stemness of tumour cells." (PMID 31258849, 2019). "Immunohistochemistry showed that Vimentin (Vim) protein was significantly up-regulated in hepatocarcinoma cells, while E-cadherin (E-cad) was down-regulated in tumor tissues." (PMID 30606744, 2019). "The most relevant immunohistochemical finding for the diagnosis of CRbC is the coexpression in tumor cells of pancytokeratin and vimentin." (PMID 31455041, 2019). "Vimentin is a cancer marker that is overexpressed in neoplasms undergoing epithelial to mesenchymal transition." (PMID 30894168, 2019). "Using the differential intensity levels of EpCAM and vimentin, we formulated an image-based tumor purity estimation to measure the tumor cell index." (PMID 31850215, 2019). "Consistently, overexpression of miR-1-3p markedly suppressed epithelial-mesenchymal transition (EMT), a process contributing to tumor metastasis, as evidenced by downregulation of the mesenchymal markers fibronectin, N-cadherin, and vimentin." (PMID 30881920, 2019). "The protein expression of vimentin, MM9, E-cadherin in tumor samples was evaluated using immunohistochemistry, and mRNA levels of N-cadherin, Snail, vimentin, TWIST, SLUG, and E-cadherin were quantified by RT-PCR." (PMID 31416135, 2019). "It has been proven in many tumours that vimentin plays an important role in tumour invasion and metastasis, and vimentin promotes GC progression by repressing E-cadherin." (PMID 31357957, 2019). "KLK6 expression resulted in significant downregulation of vimentin, a critical marker of epithelial-to-mesenchymal transition of tumour cells." (PMID 31186631, 2019). "Immunohistochemical stains show strong and diffuse staining for vimentin and pancytokeratin in tumor cells." (PMID 31623602, 2019). "The number of Ki67 positive cells was elevated in αDG+/EphA3+/vimentin+ tumour regions compared to other regions, suggesting this tumour compartment was more mitotically active." (PMID 31463571, 2019). "Considering that the invasive tumor cells were positive for vimentin, Snail and TGF-β2, we concluded that their invasion was the result of the activation of epithelial–mesenchymal transition (EMT) mechanisms." (PMID 30893803, 2019).